IGFL1P1 (IGF like family member 1 pseudogene 1)
Synonyms: IGFL-5P
Gene: Unprocessed pseudogene on chromosome 19 (46,196,238 to 46,197,323, forward strand). Ensembl gene ENSG00000268879.
Diseases named in the same sentence as IGFL1P1 in open-access papers:
IGFL1P1 is named in the same sentence as 1 disease in open-access papers, as found by Europe PMC text mining. Sharing a sentence is not in itself a finding about the gene and the disease. The quoted sentences say what the papers report.
esophageal cancer (1 paper, 2025). A primary or metastatic malignant neoplasm involving the esophagus. "Decreased levels of COL4A1, DEK, GINS1, HPCAL1, KIF4A and RBMX predicted longer survival in esophageal cancer patients, while overexpression of IGFL1P1, LRRC57A-AS1, SNHG3, ULK3 and ZFYVE19 correlated with longer survival." (PMID 41326355, 2025). "In contrast, IGFL1P1, LRRC57A-AS1, SNHG3, ULK3 and ZFYVE19 showed poor expression in esophageal cancer tissues but high expression in the combined treatment group." (PMID 41326355, 2025).